CD3D (CD3 delta subunit of T-cell receptor complex)
Description:
Part of the TCR-CD3 complex present on T-lymphocyte cell surface that plays an essential role in adaptive immune response. When antigen presenting cells (APCs) activate T-cell receptor (TCR), TCR-mediated signals are transmitted across the cell membrane by the CD3 chains CD3D, CD3E, CD3G and CD247/CD3Z. All CD3 chains contain immunoreceptor tyrosine-based activation motifs (ITAMs) in their cytoplasmic domain. Upon TCR engagement, these motifs become phosphorylated by Src family protein tyrosine kinases LCK and FYN, resulting in the activation of downstream signaling pathways. In addition of this role of signal transduction in T-cell activation, CD3D plays an essential role in thymocyte differentiation. Indeed, participates in correct intracellular TCR-CD3 complex assembly and surface expression. In absence of a functional TCR-CD3 complex, thymocytes are unable to differentiate properly. Interacts with CD4 and CD8 and thus serves to establish a functional link between the TCR and coreceptors CD4 and CD8, which is needed for activation and positive selection of CD4 or CD8 T-cells.
Synonyms: T3D; CD3DELTA; CD3-DELTA; IMD19
Tractability: Small molecule: a structure with a bound ligand is known. Antibody: an approved drug acts on it; its Gene Ontology location is reachable by antibodies, with high confidence; UniProt places it where antibodies can reach, with medium confidence; UniProt predicts a signal peptide or a membrane-spanning region. PROTAC: ubiquitination databases record sites on it; its protein half-life has been measured.
Gene: Protein-coding gene on chromosome 11 (118,334,537 to 118,342,705, reverse strand). Ensembl gene ENSG00000167286.
Subcellular location: Cell membrane
Subcellular location (Human Protein Atlas): Endoplasmic reticulum; Vesicles
Pathways (Reactome):
Immune System: Co-inhibition by PD-1; Downstream TCR signaling; Generation of second messenger molecules; Immunoregulatory interactions between a Lymphoid and a non-Lymphoid cell; Phosphorylation of CD3 and TCR zeta chains; Translocation of ZAP-70 to Immunological synapse
Vesicle-mediated transport: Cargo recognition for clathrin-mediated endocytosis; Clathrin-mediated endocytosis
Gene Ontology:
Molecular function: identical protein binding; MHC class II receptor activity; protein binding; transmembrane signaling receptor activity
Biological process: T cell receptor signaling pathway; adaptive immune response; alpha-beta T cell activation; cell surface receptor signaling pathway; positive thymic T cell selection; immune system process
Cellular component: alpha-beta T cell receptor complex; plasma membrane; T cell receptor complex; clathrin-coated endocytic vesicle membrane; cytoplasm; external side of plasma membrane; membrane
Genetic constraint (gnomAD): Loss-of-function variants: 21 observed, 22.83 expected, observed/expected ratio (o/e) 0.92, 90% interval 0.65 to 1.33. The upper end of that interval is the gene's LOEUF score, 1.33, which puts it in group 5 of 6, group 1 being the genes least tolerant of losing a copy. Missense variants: 205 observed, 223.36 expected, observed/expected ratio (o/e) 0.92, 90% interval 0.82 to 1.03. Synonymous variants: 74 observed, 85.91 expected, observed/expected ratio (o/e) 0.86, 90% interval 0.71 to 1.04.
Gene-disease validity (ClinGen):
ClinGen rates the evidence that CD3D causes each of these diseases.
immunodeficiency 19 (autosomal recessive): Definitive. Any severe combined immunodeficiency in which the cause of the disease is a mutation in the CD3D gene.
Homologues: Orthologues: chimpanzee CD3D (98% identical), macaque CD3D (94% identical), guinea pig CD3D (71% identical), pig CD3D (71% identical), dog CD3D (69% identical), rat Cd3d (69% identical), mouse Cd3d (64% identical), tropical clawed frog cd3g (33% identical). Paralogues in human: CD3G (40% identical), CD3E (25% identical).
Diseases named in the same sentence as CD3D in open-access papers:
CD3D is named in the same sentence as 98 diseases in open-access papers, as found by Europe PMC text mining. Sharing a sentence is not in itself a finding about the gene and the disease. The quoted sentences say what the papers report.
breast carcinoma (15 papers, 2019 to 2025). "For example, in the first network module (red), one of the proteins is CD3D, which has prognostic potential for breast cancer and is associated with lymphocyte infiltration and immune checkpoints." (PMID 40228208, 2025). "CD3D expression in residual breast cancer tissue, after neoadjuvant chemotherapy, was associated with improved patient outcomes." (PMID 40565031, 2025). "CD3D is implicated in several cancers, including bladder cancer, colon cancer, breast cancer, and glioblastoma." (PMID 37031292, 2023). "In addition, other studies have shown that high CD3D expression is strongly associated with poor survival in breast carcinoma." (PMID 35719985, 2022). "The tumor microenvironment (TME) of HR+/HER2- breast cancer cells is composed of CD3D+ T cells, CD68+ macrophages, COL1A1+ fibroblasts, and FLT1+ endothelial cells." (PMID 38892065, 2024). "CD3D has been found to be related to several types of cancer, such as breast cancer, colon cancer, and bladder cancer." (PMID 36802116, 2023). "Previous study has showed that CD3D is closely related to glioblastoma multiforme, cervical cancer, and breast cancer." (PMID 35152883, 2022). "Previous studies have shown that CD3D can modulate the tumor immune microenvironment and affect the prognosis and immune response of breast cancer and cervical squamous cell carcinoma." (PMID 35719985, 2022). "Some studies have shown that CD3D is involved in regulating the tumor immune microenvironment in cervical cancer, liver cancer, breast cancer and other tumors." (PMID 35719985, 2022). "Moreover, the PPI network uncovered the crucial roles of numerous proteins (e.g., FOXP3, STAT1, STAT4, FOXP3, JUN, and CD3D) in breast cancer." (PMID 36704358, 2022). "Another study showed that CD3D was the target of mir-182-5p and might be used as candidate biomarkers of breast cancer." (PMID 35152883, 2022).
Sepsis (13 papers, 2011 to 2025). Sepsis is defined as life-threatening organ dysfunction caused by a dysregulated host response to infection. "CD3D was also identified as a core gene linked to immune infiltration, with potential diagnostic utility in COVID-19 patients with sepsis." (PMID 41155463, 2025). "CD3D is involved in T cell development and signal transduction, which is an effective tool to identify patients with high or low risk of sepsis after abdominal surgery." (PMID 36199375, 2022). "In the GSE54514 control and sepsis groups, CD3D and ITPR3 (inositol 1,4,5 trisphosphate receptor type 3) had degree 33 and 43, respectively." (PMID 33667236, 2021). "CD3D was also recently identified in a microarray study comparing the expression profile of whole blood samples from surgical patients diagnosed with either SIRS or sepsis." (PMID 27015534, 2016). "Therefore, the lower expression of CD3D in whole blood may reflect the lymphopenia that occurs after sepsis or SIRS and emphasize the role of T-cell response in HAI occurrence." (PMID 27015534, 2016). "The lower expression of the hub genes (CD3D, CD3E, CD4, CD28, IL7R and LCK) was observed in sepsis samples, which was consistent in all the six hub genes." (PMID 37113759, 2023). "The lower expression of the six hub genes (CD28, CD3D, CD4, IL7R, LCK, and CD3E) was observed in sepsis samples." (PMID 37113759, 2023). "The results showed the expression level of CD3D, CD3E, CD4, CD28, IL7R, and LCK was statistically different between sepsis and normal groups." (PMID 37113759, 2023). "We also found that the expression level of CD3D, CD3E, CD4, CD28, IL7R, and LCK was statistically different between sepsis and normal groups, indicating their potential role in the development of sepsis." (PMID 37113759, 2023). "In conclusion, the present study revealed an unbalanced immune response at the transcriptome level of sepsis and identified genes for potential biomarkers of sepsis, such as ITK, CD247, MMP9, CD3D, MMP8, KLRK1, and GZMK." (PMID 35190763, 2022). "They showed that TNF, IL1-β, CD3D and PRF1 gene expressions were significantly different in patients who developed postoperative sepsis in comparison with patients who recovered uneventfully." (PMID 22027436, 2011). "Neonates with sepsis show differential hypermethylation of the CD3G and CD3D gene promoters and hypomethylation of IL10 gene promoter compared to controls without sepsis." (PMID 40927580, 2025).
Immunodeficiency (12 papers, 2013 to 2024). Failure of the immune system to protect the body adequately from infection, due to the absence or insufficiency of some component process or substance. "The CD3D gene defect, which occurs early in life, leads to severe immune deficiency, making a person susceptible to infection." (PMID 34555062, 2021). "Homozygous mutations in the CD3D gene can lead to markedly abnormal T-cell development, and thus, to early-onset immunodeficiency." (PMID 33748188, 2021). "Deficiency of Cd3d also impairs T cell-dependent functions of B cells and causes severe immunodeficiency." (PMID 31105563, 2019). "Six genes related to (a) immune checkpoints (n = 2; BTLA and CD6); (b) regulatory macrophages and T cells (n = 2; CCR7 and CD3D); and (c) immune deficiencies and unfavorable prognosis (n = 2; CD3E and FCGR2B) were down-regulated post-RT compared with pre-RT (statistical p-range: <0.0001–0.0415)." (PMID 36291815, 2022). "Additionally, studies have reported that CD3D is a molecular diagnostic marker for immunodeficiency in early infancy." (PMID 34603038, 2021). "Interestingly, researchers found that CD3D is the T cell-related marker, and CD3D defects can cause severe immunodeficiency, which indicates the potential role of CD3D in predicting the immunotherapy response." (PMID 34093667, 2021). "An elevation of TCRγδ T cells has been observed in some combined immunodeficiencies such as recombination activating gene 1,2 deficiency, CD3γ, and CD3δ, as a consequence of CMV infection or delayed-onset combined immune deficiency with granuloma and/or autoimmunity." (PMID 28747912, 2017). "Despite the high sequence homology between CD3γ and CD3δ, the clinical consequences of the corresponding immunodeficiencies (ID) in humans are very different (mild and severe, respectively), and mouse models do not recapitulate findings in human ID." (PMID 34249896, 2021). "CD3γ deficiency, unlike CD3 δ, ε, and ζ deficiency, tends to present as combined immunodeficiency with variable onset." (PMID 27222657, 2016).
melanoma (10 papers, 2016 to 2025). A malignant, usually aggressive tumor composed of atypical, neoplastic melanocytes. "CD3D, a marker of T cells relevant to adaptive immunity as well as associated with a favorable prognosis of melanoma, whereas CD38, which regulates NAD+ metabolism, marks activated B cells and plasma cells." (PMID 41271007, 2025). "We also found a higher level of additional sEV cargo CD3D in the blood plasma of melanoma (p = 0.097)." (PMID 41271007, 2025). "In AYA melanomas, the expression of key gene markers for Tregs (CD3D, FOXP3) strongly correlated with CD3+FOXP3+ cell density (Spearman’s ρ = 0.74, P < 0.0001)." (PMID 38589406, 2024). "CD3D is well reported in gastric cancer and melanoma for its role in immune cell regulation." (PMID 41271007, 2025). "In addition to the purity check upon cell sorting, potential CTL contamination in melanoma cell samples isolated from the co-cultures was checked by including a series of CTL markers on the NanoString (CD3D, CD3E, CD3G, CD8A and CD8B)." (PMID 27625650, 2016). "The overexpression of CD3D and CD38 in sEV of melanoma patient lymphatics reflects critical changes in immune cell composition and activity within the SLN." (PMID 41271007, 2025). "The markers utilized in the conducted study, as defined by Tirosh and colleagues, successfully differentiated between various cell types, including melanoma cell (MLANA, PMEL), T cell (CD2, CD3D, CD3E, CD4, CD8A)." (PMID 37620327, 2023). "Furthermore, the upregulation of key melanoma-specific cargoes: LGALS9 (p = 0.029), CD3D (p = 0.097), and CD38 (p = 0.14) in the blood plasma sEVs of melanoma patients was noted in contrast to healthy donors." (PMID 41271007, 2025). "In early reports, it was shown that Th1 cytokine mRNA for CD3δ, lymphotoxin (TNF-β), and IL-2 were significantly elevated in the ten regressing melanomas compared to the ten non-regressing melanomas." (PMID 28060744, 2017).
colon cancer (8 papers, 2021 to 2025). "CD3D is associated with ICPs and infiltrating immune cells, and its expression is positively correlated with the prognosis of colon cancer." (PMID 36146529, 2022). "CD3D has been reported to be associated with a variety of cancers, including colon cancer, bladder cancer, and glioblastoma." (PMID 35834061, 2022). "CD3D has been reported as a potential biomarker for the response to ICIs and prognosis in cancers, including colon cancer and muscle-invasive bladder cancer." (PMID 33748188, 2021). "For CD3D, its higher expression is related to a better outcome in colon cancer." (PMID 36505456, 2022). "Previous studies have shown that CD3D may serve as a prognostic maker of colon cancer, gastric cancer and other tumors; CD3E can be used as a prognostic factor of lung cancer; the expression of CD247 was associated with many cancers, including gastric cancer, head and neck cancer and ovarian cancer." (PMID 36176400, 2022).
COVID-19 (8 papers, 2021 to 2025). A disease caused by infection with severe acute respiratory syndrome coronavirus 2. "ACE (AUC: 0.923), CYP1A1 (AUC: 0.902), EME1 (AUC: 0.977), CD52 (AUC: 0.970), MYBL2 (AUC: 0.995), CDC25A (AUC: 0.998), BCL6 (AUC: 0.966) and CD3D (AUC: 0.955) showed relatively good diagnostic efficiency in distinguishing COVID-19 patients from healthy controls." (PMID 38978778, 2024). "•PPI-identified hub genes IL7R/CD2/GZMA/CD3D/FCER1A diagnose COVID-19 and diabetic nephropathy with AUC>0.80, linking immune activation to tissue damage." (PMID 41332907, 2025). "In a parallel analysis, the datasets from GSE152418 revealed pronounced differences in the expression of IL7R, CD2, CD3D and FCER1A when comparing COVID-19 samples to control samples." (PMID 41332907, 2025). "For COVID-19, the AUCs of IL7R, CD2, GZMA, CD3D, and FCER1A were 0.925, 0.934, 0.905, 0.950, and 0.998, respectively." (PMID 41332907, 2025). "The role of the remaining eight key genes (ALDH1L, EME1, PYGL, NNMT, PHGDH, CD52, CD3D, and ESM1) in COVID-19 and sarcopenia has been less studied, emphasizing their importance in future research." (PMID 38978778, 2024). "CD74, CIITA, CD3D and IL7R were downregulated in critically ill COVID-19 patients in accordance with the occurrence of altered monocyte and T lymphocyte responses." (PMID 36389738, 2022). "Based on our results, we suggest that controlling high-severity-specific markers (FOS, CXCL8, HLA-A, JAK3, ICAM1, and H2BC4) and low-severity-specific markers (IL1B, CD3D, CD4, CCL5, and SNRPB) may prevent COVID-19 progression." (PMID 41155463, 2025). "Of note, the immunoreceptor Tyr-based activation motifs (ITAMs) on CD3δ and CD3γ showed increased phosphorylation whereas the CD3ζ ITAMs showed a mixed phosphorylation pattern in the COV group, suggesting that TCR signaling is partially activated in the COVID-19 patients." (PMID 38389037, 2024).
gastric cancer (7 papers, 2020 to 2025). A primary or metastatic malignant neoplasm involving the stomach. "Univariate and multivariate analyses showed that CD3D was an independent good prognostic factor for gastric cancer (P=0.004, HR=0.677, 95%CI: 0.510-0.898 for univariate analyses; P=0.046, HR=0.687, 95%CI: 0.474-0.994 for multivariate analyses)." (PMID 35719985, 2022). "The aim of this study was to clarify the value of CD3D in the diagnosis and prognosis of gastric cancer and its role in the tumor immune microenvironment." (PMID 35719985, 2022). "We found that The expression of CD3D was correlated with tumor location, and is significantly higher in proximal gastric cancer than in distal gastric cancer (P=0.012)." (PMID 35719985, 2022). "Univariate and multivariate analyses showed that CD3D was an independent prognostic factor for gastric cancer, and patients with high expression of CD3D had a better prognosis." (PMID 35719985, 2022). "In gastric cancer patients, we found that the expression of CD3D was highly positively correlated with the expression of CD3, CD4, CD8, and PD-L1." (PMID 35719985, 2022). "The results showed that CD3D was highly expressed in gastric cancer tissues compared with paracancerous tissues (P<0.000)." (PMID 35719985, 2022). "Since CD3D was positively correlated with the expression of CD3, CD4, CD8 and PD-L1, the effect of CD3D in combination with these factors on the prognosis of gastric cancer was analyzed." (PMID 35719985, 2022). "To further observe the significance of CD3D expression in gastric cancer, we analyzed the correlation between its expression and all clinical information, such as age, gender, smoking status, and alcohol consumption." (PMID 35719985, 2022). "In our study, we found that CD3D was highly expressed in gastric cancer tissues compared with paracancerous tissues." (PMID 35719985, 2022). "However, the expression and clinical significance of CD3D in gastric cancer are still unclear and are worthy of further study." (PMID 35719985, 2022). "The correlation between CD3D expression and clinicopathological characteristics in gastric cancer." (PMID 35719985, 2022). "In addition, the CD3D positivity rate was 31.25% in gastric cancer patients with distant metastases, while it reached as high as 51.45% in patients without distant metastases, indicating a significant difference (P=0.027)." (PMID 35719985, 2022). "In summary, CD3D may play an important regulatory role in the tumor immune microenvironment of gastric cancer and may serve as a potential indicator of prognosis and immunotherapy response." (PMID 35719985, 2022). "Therefore, we further detected the expression of CD3, CD4, CD8 and PD-L1 in the tumor tissues of the included gastric cancer patients and evaluated their relationship with CD3D to explore the regulatory role of CD3D in the immune microenvironment of gastric cancer." (PMID 35719985, 2022). "Thus, CD3D may play an important role in the regulation of the immune microenvironment in gastric cancer." (PMID 35719985, 2022). "Then, immunohistochemical staining of CD3D, CD3, CD4, CD8 and PD-L1 was conducted to investigate the expression of CD3D in gastric cancer and the correlation between the expression of CD3D and tumor infiltrating lymphocytes (TILs) and PD-L1." (PMID 35719985, 2022). "Univariate logistic regression analysis found that CD3D, CD8, CD4, age, family history, tumor location, tumor size, grade of differentiation and TNM stage were all prognostic factors for gastric cancer." (PMID 35719985, 2022). "The pearson correlation coefficients between CD3D expression and CD3, CD4, CD8 and PD-L1 expression in gastric cancer." (PMID 35719985, 2022). "In addition, we further carried out multivariate analysis with these important factors, and the results showed that CD3D, CD4, and CD8 were independent prognostic factors for gastric cancer in both the univariate and multivariate analyses." (PMID 35719985, 2022).
gastric cancer (continued). "However, the expression and clinical significance of CD3D in gastric cancer are not clear." (PMID 35719985, 2022).